SLC12A2 (solute carrier family 12 member 2)
Description:
Cation-chloride cotransporter which mediates the electroneutral transport of chloride, potassium and/or sodium ions across the membrane. Plays a vital role in the regulation of ionic balance and cell volume.
Synonyms: BSC2; hNKCC1; NKCC1; BSC-2; PPP1R141; CCC1; BSC; KILQS
Tractability: Small molecule: a structure with a bound ligand is known; it belongs to a druggable protein family. Antibody: UniProt places it where antibodies can reach, with high confidence; its Gene Ontology location is reachable by antibodies, with high confidence; UniProt predicts a signal peptide or a membrane-spanning region; the Human Protein Atlas places it where antibodies can reach. PROTAC: ubiquitination databases record sites on it; its protein half-life has been measured; a small molecule that binds it is known.
Target class: Electrochemical transporter; SLC superfamily of solute carriers; Transporter; SLC12 family of cation-coupled chloride transporters
Gene: Protein-coding gene on chromosome 5 (128,083,714 to 128,189,677, forward strand). Ensembl gene ENSG00000064651.
Subcellular location: Basolateral cell membrane
Subcellular location (Human Protein Atlas): Plasma membrane; Vesicles; Basal body
Pathways (Reactome):
Transport of small molecules: Cation-coupled Chloride cotransporters
Gene Ontology:
Molecular function: ammonium channel activity; chloride:monoatomic cation symporter activity; Hsp90 protein binding; metal ion transmembrane transporter activity; protein binding; protein kinase binding; protein serine/threonine kinase binding; protein-folding chaperone binding; sodium:potassium:chloride symporter activity; potassium ion transmembrane transporter activity; transmembrane transporter activity
Biological process: ammonium transmembrane transport; cellular response to chemokine; inorganic cation import across plasma membrane; T cell chemotaxis; transepithelial ammonium transport; transepithelial chloride transport; cell volume homeostasis; cellular response to potassium ion; chloride transmembrane transport; chloride transport; gamma-aminobutyric acid signaling pathway; inorganic anion import across plasma membrane; intracellular chloride ion homeostasis; intracellular potassium ion homeostasis; intracellular sodium ion homeostasis; maintenance of blood-brain barrier; negative regulation of vascular wound healing; positive regulation of aspartate secretion; potassium ion import across plasma membrane; potassium ion transmembrane transport; regulation of matrix metallopeptidase secretion; regulation of spontaneous synaptic transmission; sodium ion import across plasma membrane; sodium ion transmembrane transport; transport across blood-brain barrier; and 6 more
Cellular component: apical plasma membrane; basal plasma membrane; cell periphery; cytoplasmic vesicle membrane; extracellular exosome; extracellular vesicle; lateral plasma membrane; neuron projection; neuronal cell body; plasma membrane; basolateral plasma membrane; cell body; cell body membrane; cell projection; cell projection membrane; membrane
Genetic constraint (gnomAD): Loss-of-function variants: 21 observed, 41.94 expected, observed/expected ratio (o/e) 0.5, 90% interval 0.35 to 0.72. The synonymous counts are far from expectation, so gnomAD's model fits this gene poorly and the ratio says little. Missense variants: 656 observed, 692.66 expected, observed/expected ratio (o/e) 0.95, 90% interval 0.89 to 1.01. Synonymous variants: 360 observed, 282.07 expected, observed/expected ratio (o/e) 1.28, 90% interval 1.17 to 1.39.
Homologues: Orthologues: chimpanzee SLC12A2 (99% identical), macaque SLC12A2 (99% identical), dog SLC12A2 (95% identical), pig SLC12A2 (95% identical), mouse Slc12a2 (94% identical), rat Slc12a2 (93% identical), rabbit SLC12A2 (90% identical), guinea pig SLC12A2 (88% identical), tropical clawed frog slc12a2 (79% identical), Drosophila melanogaster Ncc69 (45% identical), Caenorhabditis elegans nkcc-1 (41% identical), zebrafish slc12a2l (22% identical), and 4 more. Paralogues in human: SLC12A1 (58% identical), SLC12A3 (44% identical), SLC12A4 (25% identical), SLC12A6 (24% identical), SLC12A5 (24% identical), SLC12A7 (24% identical), SLC12A9 (19% identical), SLC12A8 (16% identical).
Diseases named in the same sentence as SLC12A2 in open-access papers:
SLC12A2 is named in the same sentence as 189 diseases in open-access papers, as found by Europe PMC text mining. Sharing a sentence is not in itself a finding about the gene and the disease. The quoted sentences say what the papers report.
epilepsy (44 papers, 2012 to 2025). A brain disorder characterized by episodes of abnormally increased neuronal discharge resulting in transient episodes of sensory or motor neurological dysfunction, or psychic dysfunction. "It is worth mentioning that the Slc12a2 KO mouse is viable; however, the loss of the NKCC1 protein causes deficits in neuronal proliferation (Magalhães and Rivera, 2016) and exacerbates the severity of a mouse model of epilepsy, amongst other issues." (PMID 35875665, 2022). "SLC12A5 (KCC2) is the major chloride ion extrusion transporter, and its activity balance changes with SLC12A2 are highly related to epilepsy." (PMID 41425581, 2025). "SLC12A2 (NKCC1) promotes the depolarizing response of γ-aminobutyric acid (GABA) by mediating chloride ion uptake, and its altered activity balance is closely associated with epilepsy." (PMID 41425581, 2025). "According to the previous analysis, SLC12A2 was classified in cluster 8 related to demyelinating diseases, while SLC12A5 was classified in cluster 9 related to epilepsy." (PMID 36934242, 2023). "Then, we compared mRNA levels of SLC12A2 and SLC12A5 in MS and epilepsy separately." (PMID 36934242, 2023). "Although, SLC12A2 is regarded as a target gene in epilepsy treatment, we found no significant changes in SLC12A2 expression in epileptic models, but they seemed to act more sensitively in demyelinating diseases." (PMID 36934242, 2023).
schizophrenia (27 papers, 2011 to 2025). A major psychotic disorder characterized by abnormalities in the perception or expression of reality. "For instance, the SLC12A2 gene, which encodes for NKCC1, has been reported to be a susceptibility gene for schizophrenia." (PMID 24904277, 2014). "This study shows that two SNPs in intergenic of the CTXN3 and SLC12A2 genes, rs245178 and rs698172, are associated with risk of schizophrenia in Thai population." (PMID 22643131, 2012). "Further study, it would be of interest to identify genetic variation around these SNPs affecting the expression pattern of the CTXN3 and SLC12A2 genes and test the association with risk for schizophrenia." (PMID 22643131, 2012). "A variation in SLC12A2 gene encoding NKCC1 was reported to be linked to schizophrenia." (PMID 29934975, 2018). "In humans, clinical genetic studies support an association between NKCC1 (coded by the gene SLC12A2) and schizophrenia." (PMID 35069119, 2021). "Furthermore, genetic studies have associated a gene-interplay between SLC12A2 and DISC1 with an altered risk of schizophrenia." (PMID 25889058, 2015). "Notably, Kim and colleagues found that an interaction between a single nucleotide polymorphism in the SLC12A2 gene and a single nucleotide polymorphism in the Disrupted in schizophrenia 1 (DISC1) gene increased risk for the development of schizophrenia." (PMID 24904277, 2014). "Further study is required for clarification the role of genetic variation around these SNPs in expression pattern of the CTXN3 and SLC12A2 genes, which may be involved in schizophrenia pathogenesis." (PMID 22643131, 2012). "Both CTXN3 and SLC12A2 are indicated to play a role in normal brain function, in addition, the CTXN3-SLC12A2 region is considered as the second most important region linked to schizophrenia in the meta-analysis, therefore, they may be involved in schizophrenia pathogenesis." (PMID 22643131, 2012). "Schizophrenia, a neuropsychiatric disorder, also has abnormalities in the GABAergic system where the ratios of three genes related to GABA signaling are increased: GAD1 (GAD67 and GAD25), SLC12A2 (NKCC1), and SLC12A5 (KCC2) in the prefrontal cortex." (PMID 36771011, 2023).
ischemia (20 papers, 2011 to 2023). A hypoperfusion of the BLOOD through an organ or tissue caused by a PATHOLOGIC CONSTRICTION or obstruction of its BLOOD VESSELS, or an absence of BLOOD CIRCULATION. "Astrocytes from Slc12a2 KO mice are unable to regulate their volume in response to a hyperkalemic (75 mM K+) challenge, and NKCC1 has been implicated in astrocytic swelling in pathological conditions such as ischemia and brain edema caused by liver dysfunction." (PMID 35875665, 2022).
glioblastoma (19 papers, 2012 to 2026). The most malignant astrocytic tumor (WHO grade IV). "In human glioblastoma cells, increased SLC12A2 protein expression is associated with tumor grade and cell migration." (PMID 36142368, 2022). "SLC12A2 expression is associated with glioblastoma cell invasion and aggressiveness." (PMID 31703415, 2019). "It was reported that 50 μM TMZ significantly increased SLC12A2 expression in glioblastoma PBT24 and SF8628 cell lines." (PMID 41012498, 2025). "A study revealed that NKCC1/SLC12A2 was highly expressed in Glioblastomas and it promoted EMT-like process via RhoA and Rac1 signaling pathways." (PMID 38396064, 2024). "High-grade glioblastoma cells are characterised by elevated levels of [Cl−]i, which is due to increased SLC12A2 and decreased SLC12A5 co-transporter activity." (PMID 36142368, 2022). "Inhibition of SLC12A2 suppresses glioblastoma cell invasion." (PMID 36142368, 2022). "The expression of SLC12A2, SLC12A5, and CDH2 in adult glioblastoma U87 MG and T98G control cells differs significantly." (PMID 39061990, 2024). "The study aimed to determine the expression of carcinogenesis-related SLC5A8, SLC12A2, SLC12A5, CDH1, and CDH2 in adult glioblastoma U87 MG and T98G cells and the effects of 0.5 mM, 0.75 mM, and 1.5 mM doses of VPA." (PMID 39061990, 2024). "It was reported that different VPA effect the expression of the SLC12A2 (NKCC1) and SLC12A5 (KCC2) co-transporter genes in pediatric glioblastoma PBT24 (boys) and SF8628 (girls) cells." (PMID 39061990, 2024). "The different effects of VPA on the expression of SLC12A2, SLC12A5, and SLC5A8 in PBT24 and SF8628 glioblastoma cells suggest differences in tumor cell biology." (PMID 35625705, 2022). "This study aimed to investigate the effect of 0.5 and 0.75 mM VPA on NKCC1 (SLC12A2), KCC2 (SLC12A5) and SLC5A8 (SLC5A8) co-transporter gene expressions in pediatric PBT24 (boy’s) and SF8628 (girl’s) glioblastoma cells." (PMID 35625705, 2022). "Background/Objectives: The study aimed to determine the expression of carcinogenesis-related genes, such as SLC12A2, SLC12A5, CDH1, CDH2, EZH2, and GFAP, in primary glioblastoma (WHO Grade IV; IDH-wild-type) cells from three adult women: GBM5-1, GBM5-2F, and GBM5-3F." (PMID 41012498, 2025). "The distinct effects of VPA on the expression of SLC12A2, SLC12A5 and SLC5A8 in PBT24 and SF8628 glioblastoma cells suggest differences in tumor cell biology that may be gender-related." (PMID 35625705, 2022).
Hypertension (18 papers, 2009 to 2026). The presence of chronic increased pressure in the systemic arterial system. "Increased expression of angiotensin II AT1A receptor (encoded by Agtr1a) and Na+-K+-Cl− cotransporter-1 (NKCC1, encoded by Slc12a2) in the hypothalamic paraventricular nucleus (PVN) contributes to hypertension development." (PMID 38160798, 2023). "In summary, our study unveils that DNA hypomethylation plays a crucial role in active transcription of Agtr1a and Slc12a2, two major prohypertensive genes in the brain, in the development of hypertension." (PMID 38160798, 2023). "Collectively, our findings suggest that DNA hypomethylation resulting from the DNMT/TET switch at gene promoters in the PVN promotes transcription of Agtr1a and Slc12a2 and hypertension development." (PMID 38160798, 2023). "Our study demonstrates an age-dependent increase in the transcripts of Agtr1a and Slc12a2, two critically important genes in the PVN involved in the development of hypertension." (PMID 38160798, 2023).
hearing loss (14 papers, 2020 to 2024). "Association of SLC12A2 variants with hearing loss has been reported and registered as DFNA78 in OMIM (619081)." (PMID 35248088, 2022). "Other members of the solute carrier family (SLC22A4, SLC26A5, SLC17A8, SLC12A2) have also been associated with non-syndromic hearing loss (hereditaryhearingloss.org)." (PMID 35741759, 2022). "This study has generated novel biological data associated with the pathogenicity of targeted variants in CLIC5A and SLC12A2, found in two African families, and therefore expands our understanding of their pathobiology in hearing impairment." (PMID 36035115, 2022). "SNVs in SLC12A2 are linked to NDs and variants specific to exon 21, present in NKCC1a, to hearing impairment or loss." (PMID 35448033, 2022). "We have previously reported CLIC5A and SLC12A2 variants in two families from Cameroon and Ghana, segregating non-syndromic hearing impairment (NSHI)." (PMID 36035115, 2022). "SLC12A2 is expressed in the inner ear and has been recently associated with hearing impairment in humans." (PMID 36035115, 2022). "About 80% of all SLC12A2 variant associated with hearing impairment are found in the exon 21 of the gene." (PMID 36035115, 2022). "By comprehensive genetic analysis of protein-coding sequences, we identified four candidate changes in SLC12A2 in four families with congenital, severe-to-profound hearing loss." (PMID 32294086, 2020). "No Tier 1 genes (previously identified deafness genes in humans) with autosomal dominant inheritance were among the candidate variants, and SLC12A2 was the only Tier 2 gene (genes associated with hearing loss in mouse models) among the variants." (PMID 32294086, 2020). "In conclusion, whole-exome analysis or sequencing analysis targeting 154 deafness genes of four families with hearing loss identified SLC12A2 as a novel candidate deafness gene." (PMID 32294086, 2020). "These three SLC12A2 variants were considered the best candidates for causing hearing loss in the families." (PMID 32294086, 2020). "Association of CLIC5 and SLC12A2 variants with hearing impairment in patients." (PMID 36035115, 2022). "Identification of partners that interact with the exon 21-encoded region of SLC12A2 may provide insight into the tissue-specific properties of the ion transporter isoforms, as well as the molecular pathology of hearing loss associated with SLC12A2 variants." (PMID 32294086, 2020). "Hence, to verify the role of the exon 21 variants of SLC12A2 in hearing loss, generation and investigation of animal models carrying the equivalent variants is required." (PMID 32294086, 2020). "The molecular mechanism of hearing loss could include dysfunction of the cotransporter activity of SLC12A2 caused by the exon 21 variants, and may reflect other affected roles of the exon 21-encoded region." (PMID 32294086, 2020). "Besides, mutation in SLC12A2 also leads to sensorineural hearing loss in humans." (PMID 35154281, 2022). "In addition, we investigated whether blocking another solute carrier, NKCC1 (encoded by the Slc12a2 gene), Cl–, Na+, and/or K+ ion transporter involved in hearing impairments, might also affect AJ and TJ gene expression in a wildtype-derived endothelial cell monolayer." (PMID 35496913, 2022). "Except the known deafness gene SLC12A2 discussed earlier, disrupted SLC12A1 was also reported to be involved in hearing loss." (PMID 35154281, 2022). "Among the hearing impairment genes expressed in the inner ear are CLIC5A and SLC12A2 and we have recently identified variants within both genes which were associated with hearing impairment in two families from Cameroon and Ghana, respectively." (PMID 36035115, 2022). "Using WES, we identified three variants of SLC12A2, which encodes Na+, K+, 2Cl− cotransporter 1 (NKCC1), in three independent families with segregating hearing loss." (PMID 32294086, 2020).
hearing loss (continued). "Several susceptibility genes for hearing loss are involved in potassium recycling, such as connexin genes (GJB2, GJB3), potassium channels or channel subunits (KCNQ1, KCNQ4) and Na+/2Cl-/K+ cotransporter (SLC12A2)." (PMID 39226169, 2024). "SLC12A2 variants have been identified in patients with AD nonsyndromic hearing loss (MIM 619081), with AD Delpire-McNeill syndrome (MIM 619083), or AR Kilquist syndrome (MIM 619080)." (PMID 33924653, 2021). "The gene SLC12A2 encodes a protein involved in sodium, potassium, and chloride transport essential for proper function of specific cells in the stria vascularis; however, human variants of SLC12A2 have not previously been associated with hearing loss." (PMID 32294086, 2020).
deafness (12 papers, 2014 to 2024). An inherited or acquired condition characterized by the complete loss of the ability to hear from one or both ears. "Mice with disruption of the gene Slc12a2 encoding NKCC1 are viable, but suffer from deafness, increased pain perception, and male infertility." (PMID 38066086, 2023). "Mice with disruption of the gene Slc12a2 encoding both NKCC1 splice variants (NKCC1a and NKCCb) are viable, but suffer from deafness, pain perception, and male infertility." (PMID 35935337, 2022). "The loss of SLC12A2 results in deafness in mouse models and has recently been implicated in human hearing loss." (PMID 34566577, 2021). "In mouse, mutations in genes expressed by marginal cells of the SV, including Slc12a2, Atp1b2, Kcnq1, and Kcne1, result in a loss or reduction of EP and deafness." (PMID 34566577, 2021). "Overall, our results strongly indicate that mutations influencing exon 21 of SLC12A2 represent a novel mechanism underlying deafness in humans." (PMID 32294086, 2020). "To address this question, we conditionally deleted Slc12a2 from the inner ear using the Tbx1Cre mouse line to cause deafness and vestibular impairment while leaving Slc12a2 expression intact in neuronal and glial brain cells." (PMID 29534062, 2018). "Mice with disruption of Slc12a2 (NKCC1) are viable, but suffer from peripheral deafness, postnatal hyperexcitability and anti-convulsant, pain perception and male infertility." (PMID 32413057, 2020). "Slc12a2-deficient mice have congenital, profound deafness; however, no human variant of SLC12A2 has been reported as associated with hearing loss." (PMID 32294086, 2020). "However, unlike the neuronal specific expression pattern of KCC2, NKCC1 is known more widely expressed in other organs including kidney and the respiratory system of mice, and likely plays an important role in the inner ear, as knockout of SLC12A2 in mice resulted in deafness and imbalance." (PMID 31963584, 2020).
developmental delay (6 papers, 2020 to 2025). "SLC12A2: ID13 who has hearing loss and global developmental delay is heterozygous for a novel stop variant c.2977G>T (p.(Glu993*)) in SLC12A2 (also NKCC1; MIM 600840; 5q23.3)." (PMID 33924653, 2021).